CCL3 (C-C motif chemokine ligand 3)
Diseases named in the same sentence as CCL3 in open-access papers (continued):
Sharing a sentence is not in itself a finding about the gene and the disease.
lung cancer (22 papers, 2008 to 2025). A malignant neoplasm involving the lung. "Similar expression patterns of PGRN and CCL3 were observed in CD8+ T cells isolated from the peripheral blood of patients with lung cancer." (PMID 38744851, 2024). "Specifically, PGRN expression by CD8+ T cells from peripheral blood mononuclear cells (PBMCs) was significantly higher in lung cancer patients compared to healthy individuals, whereas CCL3 levels were significantly reduced." (PMID 38744851, 2024). "First, although our experiments demonstrated the role of PGRN in immune evasion in lung cancer by regulating CCL3 release by CD8+ T cells and their cytotoxicity, the complex mechanisms must be further investigated." (PMID 38744851, 2024). "The mRNA expression of CCL3, CCL4, and CSF1 was significantly upregulated in IL17D–expressing A549 cells compared with that in control cells, whereas IL17D overexpression in the murine lung cancer cell line LLC1 increased Ccl3, Ccl4, and Il6 expression." (PMID 35939336, 2022). "We found that CCL3, CCL4, and CSF1 were significantly upregulated in IL17D–expressing human lung cancer cells, whereas Ccl3, Ccl4, and Il6 were induced in IL17D–expressing murine lung cancer cells." (PMID 35939336, 2022). "Statins inhibit the survival of lung cancer cells by inhibiting the secretion of CCL3 by lung cancer cells as well as IL-6 and CCL2 secretion by mesenchymal stromal cells, indicating the potential of statins as repurposed drugs for targeting the immune TME." (PMID 34303383, 2021). "Recent studies found that upregulation of CCL3 induces invasion and migration of human lung cancer cells A549." (PMID 33981848, 2021). "Marked changes in gene expression were measured for Ccl2, Ccl7, Ccl17, Ccl22, Ccl3, Ccl4, Il-1α, Il-1ß, and Il-1rn (inflammation), Lpo and Noxo1 (oxidative stress), and Mmp12 (inflammation/lung cancer)." (PMID 29463257, 2018). "CCL3 promotes cancer metastasis and progression in lung cancer, oral squamous carcinoma, and chondrosarcoma cells." (PMID 26713602, 2016). "Five altered cytokines in stage I lung cancer patients (CCL3, IL8, IL1β, CXCL10, sIL2Rα) were identified in plasma from subjects (n = 15) before and after resection using a 30-plex panel protein assay." (PMID 23762239, 2013). "The mean expression in lung cancer patients was significantly higher relative to controls for CCL3 and IL1β (10 and 29 fold, respectively)." (PMID 23762239, 2013). "Furthermore, high levels of IFN-γ in both murine and human lung cancers, some produced by lung cancer cells themselves, contribute to accelerated tumor growth through promoting the production of CCL3 and CCL4 by CD8+ T cells." (PMID 40553564, 2025). "We found that TREM2 was strongly associated with CCL2, CCL3, CCL13, and CCL17 in lung cancer." (PMID 39135069, 2024). "Zhang and colleagues found that upregulation of CCL3 promoted lung cancer metastasis." (PMID 34732692, 2021). "Although the data demonstrate that exposure of healthy donor PBMCs to lung cancer cell lines increases CCL3, IL8 and IL1β production by CD3+ and CD14+ PBMC fractions, it remains unclear as to the specific interaction which causes this result." (PMID 23762239, 2013). "Such cytokines upregulate CD8+ T cell production of CCL3 and CCL4, which alter Treg trafficking and ultimately contribute to the accelerated growth of lung cancer." (PMID 40553564, 2025). "RT-qPCR analyses of CCL2, CCL3, CCL13, and CCL17 revealed that the transcription level of CCL2 in lung cancer was notably elevated compared to that in healthy lung." (PMID 39135069, 2024). "The Macro-1 cluster was transcriptionally similar to tissue-resident macrophages as reported in primary ccRCC, breast and lung cancers, and expressed markers such as SEPP1, FOLR2, CCL3, CCL4, and CXCL12." (PMID 38281962, 2024).
lung cancer (continued). "In summary, the current study demonstrates that Spi-B-positive lung cancer cells play an important role in increasing TAM recruitment by upregulating the expression of various cytokines, such as CSF2, IL6, CCL3, and CCL4." (PMID 34141615, 2021). "Recently, a report from Zhang and group have suggested that treatment with BAP promotes the migration and invasion of lung cancer cells through up-regulating the expression of cytokine IL8 and chemokines C-C motif Ligand 2 (CCL2) and CCL3." (PMID 31252679, 2019). "PBMC gene expression of CCL3, IL8 and IL1β was higher in lung cancer patients compared to the same patients at each of four sequential timepoints after removal of their tumors, while CXCL10 and IL2Rα were essentially unchanged." (PMID 23762239, 2013). "Furthermore, IFN-γ neutralization alone resulted in an overall reduction of CCL3 and CCL4 produced by CD8+ T cells in the lung cancer tumor bed." (PMID 40553564, 2025). "Additionally, I-309/CCL1, macrophage inflammatory protein 1α (MIP-1α)/CCL3 and granulocyte colony-stimulating factor (G-CSF) from TAM increase CX3CL1 expression on lung cancer cells." (PMID 32466280, 2020). "Third, because neutrophils were nearly absent in public scRNA-seq data of lung cancer, independent validations of the hypothesis regarding CCL3+ neutrophils and SPP1+ TAMs were not available." (PMID 36869384, 2023). "Intracellular CCL3, IL8 and IL1β were detected in the CD3+ fraction (T cells) of healthy donor PBMCs which had been co-cultured with either lung cancer cell line, but not in those cultured in the absence of lung cancer cells." (PMID 23762239, 2013). "Taken together, the data suggest that healthy donor PBMCs increase their expression of CCL3, IL8 and IL1β (with little or no increases in CXCL10 and IL2Rα) when they are exposed to lung cancer cells (Figures 4and5)." (PMID 23762239, 2013).
Alzheimer disease (16 papers, 2005 to 2025). A progressive, neurodegenerative disease characterized by loss of function and death of nerve cells in several areas of the brain leading to loss of cognitive function such as memory and language. "This network contains the proinflammatory cytokine Il1a, previously associated with Alzheimer’s disease, development and plasticity, immune associated genes (Cd80, Cr2, Cd27, Dapp1) and chemokines (Ccl3, Ccl4, Ccl21)." (PMID 23742273, 2013). "Interestingly, CCL3 has been shown to be implicated in the trafficking of key effector cells to the brain during MS and its animal model experimental autoimmune encephalomyelitis, Alzheimer's disease, seizure disorders, and viral as well as bacterial neuroinflammation." (PMID 28626344, 2017). "In our opinion, an understanding of the CCL3 role seems to be highly important in neurodegenerative processes, especially due to its changes being associated with TBI, temporal lobe epilepsy, Alzheimer’s disease, and neuropathy." (PMID 37190544, 2023). "Ccl3 is released by stimulated brain endothelial cells, and it has been reported that it may be elevated in brain vessels of Alzheimer’s disease patients." (PMID 23285140, 2012). "Early intraneuronal accumulation of toxic amyloid in a mouse model of Alzheimer’s disease was recently shown to initiate inflammatory gene expression of chemokines CCL2 and CCL3 in pyramidal neurons of the hippocampus, thus demonstrating that neurons have the capacity to initiate such signaling." (PMID 32943056, 2020). "As CCL3 and CCL4 are key proinflammatory chemokines and inflammation is key in the progression of human diseases, the link between IDE and chronic diseases such as Alzheimer’s disease may be in part due to the role of IDE in controlling the inflammation." (PMID 25636406, 2015).
fibrosis (16 papers, 2010 to 2023). the formation of excess fibrous connective tissue in an organ or tissue in a reparative or reactive process. "CCL3-deficient mice, for instance, showed size reduced granuloma, lower fibrosis and lower EPO activity in the liver." (PMID 32431709, 2020). "CCL3 is similarly increased in the skin of SSc subjects and can induce fibrosis in an SSc murine model." (PMID 36014018, 2022). "We here aimed to investigate the effects of the CC chemokine CCL3, also known as macrophage inflammatory protein-1α, in two different fibrosis models." (PMID 23799074, 2013). "We have previously demonstrated that Ccl3−/− and Ccr5−/− mice exhibit reduction in BLM-induced fibrosis and the number of CD45+Col-I+CCR5+ fibrocytes in the lungs, together with suppressed CXCL12 expression." (PMID 29203799, 2017). "In addition, CCL5 and its related CCR5 ligand CCL3 and CCL4 are upregulated in the liver of patients with fibrosis." (PMID 33623529, 2021). "In line, hepatic mRNA expression of the chemokines ccl2 (F0-1 compared to F4 fibrosis, p = 0.0088) and ccl5 (F0-1 compared to F4 fibrosis, p<0.0001), but not of ccl3, was strongly up-regulated in fibrosis." (PMID 20548789, 2010). "The CCR2-CCR5 antagonist, cenicriviroc, which blocks chemotactic signaling of CCL2 (MCP-1), CCL3 and 4 (MIP-1α and β), and CCL5 (RANTES), showed encouraging phase 2b study results of improving fibrosis without worsening NASH activity and a phase 3 study is currently under way." (PMID 30643981, 2019).
co-infection (15 papers, 2009 to 2025). "Coinfection increased damage to the nasal tissue and increased production of the chemokine CCL3." (PMID 35044807, 2022). "Those with Plasmodium mono-infection had higher levels of IL-4, IL-6, IL-10, IL-12, IL-13, IL-17A, IFN-γ, and MIP1-α/CCL3 compared with DENV mono-infection or co-infection; those with Plasmodium mono-infection had more cough than those with DENV mono-infection." (PMID 27128316, 2016). "In addition, co-infection significantly regulated the mRNA expression of several chemokine and chemokine receptor genes, including CCL3 (1.62-fold), CX3CL1 (1.7-fold), CXCL16 (0.56-fold), CCR1 (2.23-fold), and CXCR4 (1.55-fold)." (PMID 25906258, 2015). "Surprisingly, only two chemokines involving neutrophil recruitment were modulated after L. major (co-)infection: a clear increase was detected for CCL3 and CXCL2, although statistically not significant." (PMID 34310619, 2021). "To examine the immune profile of individuals with co-infection, we compared the concentration of 15 immune markers (IL-1β, IL-6, IL-8, TNF-α, IL-7, G-CSF, MCP-1/CCL2, MIP-1-α/CCL3, IL-12, IFN-γ, IL-13, IL-17A, GM-CSF, IL-10, and TGF-β1) among the three groups using Kruskal-Wallis ANOVA." (PMID 27128316, 2016). "MIP-1α/CCL3 play an important role in recruiting macrophages, dendritic cells and T cells to site of infection and lymphoid organs, a task perceived to likely contribute to the dangers of schistosomiasis and HIV-1 co-infection." (PMID 19852800, 2009). "The aim of our study was to determine the plasma MIP-1α/CCL3 concentration in S. haematobium infected and uninfected humans at baseline and at three months after treatment with praziquantel and the influence of HIV-1 co-infection." (PMID 19852800, 2009).
periodontal disease (15 papers, 2010 to 2024). "It has also been shown that MIP-1α/CCL3-positive cells increase in number with increasing severity of periodontal disease." (PMID 24151615, 2013). "Additionally, gingival fibroblasts also secrete the chemokine MIP-1α/CCL3 implying on monocytes chemoattraction in periodontal disease as well as TGF-β that induces the expression of pro-collagen type I." (PMID 24646168, 2014).
Cognitive impairment (14 papers, 2019 to 2025). Abnormal cognition is characterized by deficits in thinking, reasoning, or remembering. "The loss of CCL3 or CCR5 rescues the cognitive impairments and synaptic dysfunctions and reduces the inflammatory response induced by Aβ peptides." (PMID 37511507, 2023). "Neuroinflammation is one of the main causes of cognitive disorders and diseases, and current research confirms that CCL3 can be involved in neuroinflammation, suggesting that CCL3 may contribute to the generation of neurological disorders, such as AD." (PMID 39011039, 2024). "The improvement in cognitive impairment observed in P2X7-deficient APPPS1 mice could be attributed to the lower level of CCL3 production associated with a reduction in CD8+ T cells in the brain." (PMID 37511507, 2023). "In addition, an increase in CCL3 levels was associated with T cell infiltration in the hippocampus of transgenic mice developing neurofibrillary tangles; moreover, in that model, T cell depletion improved cognitive impairments." (PMID 29934546, 2019). "In wild-type mice, intracerebroventricular injection of Aβ1-40 resulted in increased expression of CCL3, followed by astrocytosis, microgliosis, and neuroinflammation, finally leading to cognitive impairment." (PMID 35821178, 2022). "Ccl3 is a known activator of Jak-Stat signaling during prion-induced gliosis, and deletion of Tnfrsf1 reduces the number of amyloid plaques and cognitive deficits in AD mouse models." (PMID 31959236, 2020). "Among the 52 inflammatory/immune proteins positively correlated with EDII score, six proteins (CXCL10, CCL3, HGF, OPG, CDCP1, NFATC3) were significantly associated with increased odds of incident cognitive impairment after adjusting for demographic characteristics and cardiovascular risk factors." (PMID 36737481, 2023). "Furthermore, the cognitive deficits and synaptic dysfunction induced by intracerebral injections of Aβ peptides were reduced in CCL3 and CCR5 knock-out mice." (PMID 29934546, 2019). "In this paper, we review the roles and regulatory mechanisms of pro-inflammatory chemokines (CCL2, CCL3, CCL4, CCL5, CCL11, CCL20, and CXCL8) in cognitive impairment." (PMID 39011039, 2024). "Results provide insights into how inflammatory nutritional patterns are associated with an immune-related proteome and identify a group of proteins (CXCL10, CCL3, HGF, OPG, CDCP1, NFATC3, ITGA11) related to future cognitive impairment over a 14-year follow-up period." (PMID 36737481, 2023). "Similarly, in non-AD mice, subchronic intracerebroventricular injection of CCL3 resulted in inhibition of LTP and cognitive deficits, processes mediated by CCR5, as its antagonist abolished these effects." (PMID 35821178, 2022).
multiple sclerosis (14 papers, 2005 to 2025). A progressive autoimmune disorder affecting the central nervous system resulting in demyelination. "Through sophisticated analyses, we identified four cytokines with limited association with each other, that discriminated between patients with multiple sclerosis and healthy controls, namely, CCL3, IL-12B, CXCL10 and IL-8." (PMID 36756308, 2023). "The chemokine MIP-1α or CCL3, involved in CNS inflammation and in multiple sclerosis, has been reported to be generated by LPS-treated mouse, rat and human microglia cells in vitro." (PMID 24675728, 2014). "Our recent genetic scans in families identified haplotypes in the genes of CCL2, CCL3 and CCL11-CCL8-CCL13 which showed association with multiple sclerosis." (PMID 15730561, 2005). "Some authors suggest the prognostic role of CCL3 in autoimmune diseases such as multiple sclerosis." (PMID 39231178, 2024). "Interestingly, MIP-1α, also named CCL3, is an inflammatory chemokine associated with multiple sclerosis (MS), an autoimmune and inflammatory disease that affects brain and spinal cord functions, through demyelination of nerves, causing irreversible damages of the CNS." (PMID 34767551, 2021). "CCL3, IL-12B, CXCL10 and IL-8 discriminated between multiple sclerosis patients and controls, but only IL-12B differed between patients with relapsing-remitting and progressive multiple sclerosis." (PMID 36756308, 2023). "Assessing 15 representative signature genes in patients with multiple sclerosis, we find that TH1/17 cells have elevated expression of CXCR3 and reduced expression of IFNG, CCL3, CLL4, GZMB, and IL10 compared to healthy controls." (PMID 29150604, 2017).
psoriasis (14 papers, 2016 to 2025). An autoimmune condition characterized by red, well-delineated plaques with silvery scales that are usually on the extensor surfaces and scalp. "Among others, important psoriasis-associated target genes of IκBζ include certain chemo- and cytokines (e.g., Cxcl1, Cxcl2, Cxcl5, Ccl3, and Il17c) as well as antimicrobial proteins, such as S100 calcium-binding proteins (e.g., S100a9), β-defensin-2 (Defb4), and lipocalin-2 (Lcn2)." (PMID 31622280, 2019). "In our study, we also observed significantly increased CCL3/4 (CCR5 ligands) expression in the inflamed skin tissue of mice with psoriasis." (PMID 38566145, 2024). "Cells within a single CD8 TEM cluster enriched among PSO subjects (cluster 11) showed a strong upregulation of CCL4, a CD8+ T cell recruiting chemokine associated with psoriasis, along with other inflammatory cytokines and chemokines (TNF, IFNG, CCL3, CCL4L2)." (PMID 35309349, 2022). "We had found L-THE regulated chemokine signaling pathway and IL-17A signaling pathway associated genes, such as CXCL2, CCL3 and CCL4 in skin tissues from mice with psoriasis." (PMID 34381369, 2021). "Patients suffering from psoriasis are characterized by high CCL3 serum concentration that strongly correlates with increased degradation of Foxp3 mediated by K48-linked polyubiquitination." (PMID 32117202, 2019). "In T cells, NFATc1 stimulates the expression of several genes that are highly expressed during psoriasis, as the Ccl3 and Ccl4 chemokine genes." (PMID 27222343, 2016). "In addition, real-time PCR of skin tissue showed similar results, and ccl3 expression increased threefold in IMQ-induced psoriasis." (PMID 38566145, 2024). "Proteins related to the central disease‐driving pathways of psoriasis, namely the TH1 (CCL3, CCL4, CXCL9, CXCL10, CXCL11, TNFα) and TH17 pathway (CXCL1, CCL20, IL‐17A, IL‐12B) were found elevated in lesional skin across both studies." (PMID 40970551, 2025). "The heatmap showed that C–C motif chemokine ligands (Ccl3, Ccl4, Ccl5, Ccl17, Ccl19-Ps2, and Ccl22) were expressed at higher levels in IMQ-induced psoriasis." (PMID 38566145, 2024). "Chemokines, including CCL3 and CCL5, participate in the pathogenesis of psoriasis by recruiting and activating T cells, macrophages, and neutrophils." (PMID 37111171, 2023). "This phenomenon is mediated by the activation of the protein kinase B (PKB)α/Akt1 pathway, but the precise mechanism of how CCL3 and PKB induce polyubiquitination of Foxp3 in psoriasis is still under investigation." (PMID 32117202, 2019).
autoimmune disease (12 papers, 2015 to 2025). A disorder resulting from loss of function or tissue destruction of an organ or multiple organs, arising from humoral or cellular immune responses of the individual to their own tissue constituents. "The role of CCL3 in autoimmune diseases is seldom discussed in the literature." (PMID 33408682, 2020).